IGFBP3 (insulin like growth factor binding protein 3)
Diseases named in the same sentence as IGFBP3 in open-access papers (continued):
Sharing a sentence is not in itself a finding about the gene and the disease.
non-small cell lung carcinoma (21 papers, 2004 to 2025). A group of at least three distinct histological types of lung cancer, including non-small cell squamous cell carcinoma, adenocarcinoma, and large cell carcinoma. "The stage I non-small cell lung cancer patients, whose tumors harbor the high IGFBP3 expression caused by an unmethylated promoter, had a trend towards increased disease-free survival." (PMID 33712045, 2021). "IGFBP3 hypermethylation is significantly associated with poor prognosis in stage I non-small-cell lung cancer." (PMID 24964199, 2014). "We have also demonstrated that IGFBP-3 exhibits potent IGF-independent antiangiogenic activities in non-small cell lung cancer (NSCLC) cells, HNSCC cells, and HUVECs in vitro and in vivo." (PMID 25945837, 2015). "Promoter hypermethylation has been proposed as a mechanism responsible for transcriptional silencing of IGFBP3 in hepatocellular carcinoma, non-small cell lung carcinoma and very recently in cancers of the bladder and ovary." (PMID 17453001, 2007). "Non-small cell lung carcinoma patients with methylation of IGFBP3 had significantly poorer overall survival probability compared with those without methylation." (PMID 17453001, 2007). "An inverse role for IGFBP-3 in lung tumorigenesis is supported by the observation that constitutive expression of IGFBP-3 inhibits the growth of non-small-cell lung cancer." (PMID 15354219, 2004). "Although loss of IGFBP3 expression results in the reduction of tumor cell sensitivity to cisplatin in non-small cell lung cancers, we did not consistently observe similar effects of IGFBP3 on cisplatin resistance in OEC-M1 and TW2.6 cells." (PMID 33712045, 2021). "However, IGFBP-3 promoter methylation and decreased expression lead to poor prognosis of non-small cell lung cancer." (PMID 33414813, 2020). "IGFBP3 expression was significantly down-regulated in cisplatin-resistant non-small cell lung cancer (NSCLC) cells, and overexpression of IGFBP3 enhanced the cisplatin response by blocking IGF1 signaling." (PMID 36660244, 2023). "IGFBP3 activates the XBP1/IGFBP3/MMP-9 pathways to regulate the invasion and metastasis of non-small cell lung cancer (NSCLC) cells." (PMID 35011220, 2022). "IGFBP3 was previously reported to interact with and inactivate ERK1/2 by inhibiting ERK1/2 phosphorylation in human non-small cell lung cancer." (PMID 29075359, 2017). "In several non-small cell lung cancer (NSCLC) cell lines, IGFBP-3 acts as a potent inhibitor of IGF-1R signaling by interfering with both the MAPK and PI-3K/Akt signaling pathways, resulting in growth arrest and inducing apoptosis." (PMID 23185474, 2012). "The present study shows that insulin-like growth factor binding protein-3 (IGFBP-3) inhibits the migration and invasion of non-small cell lung cancer (NSCLC) and head and neck squamous cell carcinoma (HNSCC) cells in vitro and the development of metastasized tumors in vivo." (PMID 33801272, 2021). "In addition, patients with non-small cell lung cancer (NSCLC) had higher IGF1 and lower IGFBP-3 and IGFBP-7 serum and tumor tissue concentrations compared to patients with noncancerous lung diseases." (PMID 31565100, 2019).
pancreatic cancer (21 papers, 2007 to 2025). "The conditioned medium from pancreatic cancer cells contained high IGFBP3 and caused significant myofiber wasting, which was prevented by IGFBP3 knockdown or neutralizing antibody." (PMID 32858949, 2020). "In contrast, the increase in IGF1R expression in cells with a lower level of IGFBP-3 expression was associated with more advanced pancreatic cancer and worsened the prognosis." (PMID 31565100, 2019). "We further demonstrated that IGFBP-3, which is abundantly produced in pancreatic cancer cells, causes muscle wasting through both impaired myogenesis and enhanced myotube protein degradation via, at least, inhibition of IGF/PI3K/AKT signaling." (PMID 26975989, 2016). "Further investigation is necessary to elucidate the precise mechanism of TPX2 and its association with IGFBP-3 to establish a novel molecular targeting treatment for pancreatic cancer." (PMID 25914189, 2015). "The present study examined IGF1R and cell surface-associated IGFBP3 expression in patients with pancreatic cancer." (PMID 23962053, 2013). "In a cross-classification, however, a high concentration of IGF-I with concurrently low levels of IGFBP-3 was related to an increased risk of pancreatic cancer (OR=1.72, 95% CI 1.05–2.83; P-interaction=0.154)." (PMID 22315049, 2012). "Two smaller studies have evaluated the association of IGF-I and IGFBP-3 with pancreatic cancer risk." (PMID 17533398, 2007). "IGF1R signaling might be associated with tumor aggressiveness, and IGFBP3 might show antiproliferative effects in pancreatic cancer." (PMID 23962053, 2013). "However, it is noteworthy that individuals with high circulating IGF-I and low IGFBP-3 levels have an increased risk of pancreatic cancer, compared with those with low IGF-I and high IGFBP-3 concentrations." (PMID 22315049, 2012). "We also examined whether other factors that are either well-known risk factors for pancreatic cancer or are associated with IGF-I concentration modified the effect of IGF-I or IGFBP-3 on pancreatic cancer risk." (PMID 22315049, 2012). "We hypothesized that elevated levels of IGF-I and IGF-II and/or depressed levels of IGFBP-3 would predict an increased risk of pancreatic cancer." (PMID 17533398, 2007). "Thus, as in the current study, prior analyses of different patient populations have not supported a significant association between prediagnostic plasma levels of IGF-I or IGFBP-3 and the risk of pancreatic cancer." (PMID 17533398, 2007). "Additionally, we evaluated the combined effect of IGF-I and IGFBP-3 on pancreatic cancer risk by categorizing the plasma markers into tertiles and constructing a 3 × 3 table." (PMID 17533398, 2007). "We conducted a nested case–control study within four large, prospective cohorts to investigate whether prediagnostic plasma levels of IGF-I, IGF-II, and IGFBP-3 were associated with pancreatic cancer risk." (PMID 17533398, 2007). "However, on the basis of the results of a subanalysis, it cannot be excluded that a relatively large amount of IGF-1 together with very low levels of IGFBP-3 might still be associated with an increase in pancreatic cancer risk." (PMID 22315049, 2012). "Therefore, we stratified our analysis by circulating C-peptide concentration to evaluate whether the association between IGF-1 and IGFBP-3, and pancreatic cancer was different in individuals with high or low C-peptide levels." (PMID 22315049, 2012). "In conclusion, our results generally do not support the hypothesis that circulating levels of IGF-1 and IGFBP-3, or the molar IGF-I/IGFBP-3 ratio are associated with the risk of pancreatic cancer, which confirms the results of most previous prospective studies." (PMID 22315049, 2012).
pancreatic cancer (continued). "To further investigate whether plasma IGF-I, IGF-II, and IGFBP-3 levels are associated with the risk of pancreatic cancer, we performed a nested case–control study using the combined resources of four large prospective cohort studies, with blood samples collected before cancer diagnosis." (PMID 17533398, 2007). "Several data suggest that IGFBP-3 plays an important role in human pancreatic cancer-induced cachexia." (PMID 35408999, 2022). "In this study we analyzed the gene expression profile and identified that IGFBP3 is dramatically induced in pancreatic tumors." (PMID 26975989, 2016). "As the IGFBP3 exhibited the highest induction in both pancreatic tumor datasets, we proposed that pancreatic tumors probably communicate to muscle cells via production of IGFBP-3." (PMID 26975989, 2016). "In contrast, PDAC show a very high overexpression of IGFBP3, confirming the results of studies on pancreatic cancer cell lines." (PMID 27539223, 2016). "Further study is necessary to elucidate the regulatory interaction between TPX2 and IGFBP-3 in pancreatic cancer and other types of cancers." (PMID 25914189, 2015). "The present study aimed to elucidate the clinicopathologic role of insulin-like growth factor-1 receptor (IGF1R) and IGF binding protein-3 (IGFBP3) in patients with pancreatic cancer." (PMID 23962053, 2013). "In this study, IGF1R and IGFBP3 expression was examined, and their potential roles as prognostic markers in patients with pancreatic cancer were evaluated." (PMID 23962053, 2013). "The present study suggests that combined evaluation of IGF1R expression and IGFBP3 expression is a useful prognostic factor in pancreatic cancer, especially with clinical stage II tumors." (PMID 23962053, 2013). "Both high IGF1R expression and low IGFBP3 expression represent useful prognostic markers for patients with curatively resected pancreatic cancer." (PMID 23962053, 2013). "In agreement with previous microarray studies, the present study has demonstrated that IGFBP3 is overexpressed in pancreatic cancer and can differentiate cancerous from benign tissue." (PMID 21245863, 2011). "A limitation of our study is an inability to correlate the risk of pancreatic cancer with long-term levels of these plasma markers, since IGF-I, IGF-II, and IGFBP-3 were measured at a single point in time." (PMID 17533398, 2007). "In the pancreatic cancer dataset, IGFBP3 showed an increase during late development stages." (PMID 34831349, 2021). "Interestingly, IGFBP3 has been demonstrated to be a pancreatic cancer biomarker in clinical trials and to induce muscle wasting in vitro." (PMID 34831349, 2021). "Moreover, conditioned medium from Capan-1 pancreatic cancer cells, which contains abundant IGFBP-3, significantly induces muscle cell wasting." (PMID 26975989, 2016). "Our results demonstrated that pancreatic cancer cells induce muscle wasting via IGFBP-3 production." (PMID 26975989, 2016). "IGFBP3 may be overexpressed due to stressful conditions to downregulate growth and allow the pancreatic cancer cell to survive in an adverse environment with limited resources." (PMID 27539223, 2016). "We first measured the IGFBP-3 level in Capan-1 pancreatic cancer cells." (PMID 26975989, 2016). "We next examined whether Capan-1 pancreatic cancer cells escape from IGFBP-3 inhibition in a similar manner." (PMID 26975989, 2016). "Additionally, overexpression of IGFBP3 was found in pancreatic cancer cells and has been shown to promote metastases in pancreatic endocrine neoplasms." (PMID 27539223, 2016). "Thus, our results indicated that Capan-1 pancreatic cancer cells escape from IGFBP-3 inhibitory effects." (PMID 26975989, 2016). "Capan-1 cells produce multiple secreted proteins that might contribute to myotube wasting, thus our results indicated that pancreatic cancer cells induce myotube wasting via, at least, IGFBP-3 secretion." (PMID 26975989, 2016).
pancreatic cancer (continued). "The results also implied that the antiangiogenic effect of TPX2 siRNA in pancreatic cancer cells may be partly explained by the upregulation of IGFBP-3." (PMID 25914189, 2015). "Moreover, increased expression of IGFBP-3 upon treatment with TPX2 siRNA was observed in three pancreatic cancer cell lines such as KLM1, KP4, and Panc1 by Western blot analysis and real-time RT-PCR." (PMID 25914189, 2015). "The results also implied that the antiangiogenic effect observed in TPX2 siRNA-treated pancreatic cancer cells may be partly explained by the upregulation of IGFBP-3." (PMID 25914189, 2015). "Additional mutual adjustment of IGF-I and IGFBP-3 also did not strongly change the observed associations with pancreatic cancer." (PMID 22315049, 2012). "Since circulating levels of IGF-I and IGFBP-3 have been correlated with the risk of several other malignancies, our results do demonstrate that a similar association with pancreatic cancer risk is unlikely to be present in participants from our four cohorts." (PMID 17533398, 2007). "This is rather surprising, since high serum levels of IGFBP3 are supposed to inhibit IGF1, thereby reducing the availability of a relevant growth factor for PDAC and the relative levels of IGFBP3 and IGF in serum have been associated with risk of pancreatic cancer, at least in some studies." (PMID 27539223, 2016). "We next assessed whether pancreatic cancer cells induce myotube wasting via IGFBP-3 production." (PMID 26975989, 2016). "Thus we propose that pancreatic tumors result in muscle wasting via secretion of IGFBP-3." (PMID 26975989, 2016). "Because of the inconsistencies of previous studies, we examined the association between IGF-I, IGFBP-3, and pancreatic cancer in the prospective European Prospective Investigation into Cancer and Nutrition (EPIC) cohort, including more than 400 incident cases of pancreatic cancer." (PMID 22315049, 2012). "Circulating levels of IGF-I or IGFBP-3 were not related to the risk of pancreatic cancer." (PMID 22315049, 2012). "Furthermore, the differential expression patterns of SPINK1, PSCA and IGFBP3 may be of value in the differentiation of pancreatic cancer from chronic pancreatitis." (PMID 21245863, 2011). "The analysis lead to the identification of TIMP-1, FN-1, SPARC, IGFBP-3, LGALS3BP, and GREM1 as the most upregulated glycoproteins in early-stage pancreatic tumor tissues as compared to controls." (PMID 40345589, 2025). "It downregulates the levels of HIF-1α, GLUT-1, and VEGF in pancreatic carcinoma and inhibits the level of MMP-2, MMP-9, uPA, and VEGF in TRAMP mouse by downregulating IGF-I/IGFBP-3 signaling." (PMID 38611849, 2024). "In 42 primary pancreatic tumors the RNA-expression of the FLI1 targets DKK1, INPP5D, IGFBP3 and additionally two members of the Wnt/β-catenin pathway, namely BCL9 and BCL9L, was investigated using quantitative real time PCR." (PMID 27539223, 2016). "Clinicopathological features of 122 patients with curatively resected pancreatic cancer were retrospectively reviewed, and expression of IGF1R and IGFBP3 was immunohistochemically analyzed." (PMID 23962053, 2013). "However, the lack of association between IGF-I, IGF-II, or IGFBP-3 and pancreatic cancer in cases and matched controls with eight or more years between plasma collection and cancer diagnosis is reassuring that we are not missing a large effect of these plasma markers." (PMID 17533398, 2007). "Except for IGFBP3 which hadn’t been found in HPA, as we predicted, protein expressions of PTGS2 (p < 0.01) and TOP2A (p < 0.001) were higher in pancreatic tumor tissue, which was consistent with their correlation with poor survival of PAAD patients." (PMID 36003146, 2022). "Interestingly, both IGFBP3 (two probes, more than eight folds) and IGFBP5 (three probes, more than 3 folds) are dramatically increased in both pancreatic tumor datasets, whereas, IGFBP2 is significantly decreased in both datasets." (PMID 26975989, 2016).
pancreatic cancer (continued). "In pancreatic adenocarcinomas the Akt pathway is activated by IGF and the ratio of IGF and its inhibitor IGFBP3, another target of EWS/FLI1, may play a role in the development of pancreatic cancer." (PMID 27539223, 2016). "The upregulation of IGFBP-3 induced by TPX2 silencing may be at least partly responsible for the inhibitory effect on proliferation and angiogenesis in pancreatic cancer cells." (PMID 25914189, 2015). "Decreased IGFBP3 production and increased IGF1R expression in pancreas tumors might enhance the tumorigenesis and cell motility as previously reported." (PMID 23962053, 2013). "We examined the association of components of the IGF axis in association with the risk of pancreatic cancer in the largest prospective study, so far without finding any indication for an association with the circulating levels of IGF-I and IGFBP-3." (PMID 22315049, 2012). "We did not observe an increase in risk with increasing IGF-I/IGFBP-3 molar ratio, but did observe that those participants with high IGF-I levels above the median and low IGFBP-3 concentrations had an increased risk of pancreatic cancer." (PMID 22315049, 2012). "Excess IGFBP5 has been shown to regulate myotube differentiation probably via modulation of IGF-2 signaling, however, whether IGFBP-3, which predominantly binds to IGF-1 and exhibits the greatest induction in pancreatic tumors, affects myogenesis is largely unknown." (PMID 26975989, 2016). "Interestingly N-glycosilation levels were increased in pancreatic cancer samples,] from proteins such as mucin-5AC (MUC5AC), carcinoembryonic antigen-related cell adhesion molecule 5 (CEACAM5), insulin-like growth factor binding protein 3 (IGFBP3) and galectin-3 binding protein (LGALS3BP)." (PMID 31349663, 2019).
glioblastoma (20 papers, 2009 to 2024). The most malignant astrocytic tumor (WHO grade IV). "High IGFBP-3 staining in glioblastoma patients was significantly associated with shorter survival, and was described as “mostly confined to the cytoplasm” although some positive nuclei were also evident." (PMID 29623068, 2018). "IGFBP3 expression is associated with the survival and proliferation of glioblastoma." (PMID 37088808, 2023). "High IGFBP-3 expression in glioblastoma (GBM) tissue has been associated with either better or worse patient outcomes." (PMID 35597813, 2022). "On the other hand, GalNAc-T14 has been also shown to inhibit IGFBP-3-induced cell proliferation and colony formation in glioblastoma cells." (PMID 32443727, 2020). "In this line, the interaction of humanin and circulating IGFBP-3 (IGF binding protein 3) inhibited IGFBP-3-induced cell death on human glioblastoma cells." (PMID 31225450, 2018). "A similar finding was reported in brain tumors, with highest IGFBP-3 levels by both gene expression and IHC found in glioblastoma (grade IV) compared to normal brain and astrocytomas of lower grade." (PMID 29623068, 2018). "Castells and colleagues reported that the expression values from only four transcripts (CHI3L1, LDHA, LGALS1, and IGFBP3) were able to distinguish two survival groups in Glioblastoma." (PMID 27121858, 2016). "Similarly, targeting IGFBP3 suppresses glioblastoma invasion in vitro and tumor growth in vivo by reducing PD-L1 expression." (PMID 38326861, 2024). "Moreover, insulin-like growth factor (IGF)-binding protein-3 (IGFBP3) is a miR-21 target gene promoting glioblastoma tumorigenesis." (PMID 37047075, 2023). "In addition, IGFBP3 has been convinced to correlate with patients response to radiotherapy and chemotherapy in glioblastoma." (PMID 37397026, 2023). "However, raised levels of IGFBP3 are correlated with reduced survival in glioblastoma multiforme." (PMID 33282953, 2020). "Moreover, miR-21 promotes glioblastoma initiation through down-regulating IGFBP3." (PMID 28060761, 2017). "To further validate the contribution of these pathways to 12ADT-mediated cytotoxicity, we designed CRISPR guides against three target genes (ERN1, IGFBP3, IGFBP5) and transfected them separately into U251 glioblastoma cells." (PMID 32433555, 2020). "Inhibition of IGFBP3, another FAM20C substrate and a downstream effector of the YTHDF2-MYC axis in glioblastoma stem cells (GSCs), decreases GSC viability without affecting NSCs and impairs glioblastoma growth in vivo." (PMID 36825005, 2023).